VENTX (VENT homeobox)
Description:
May be involved in ventralization.
Synonyms: HPX42B; VENTX2; NA88A
Tractability: No criterion of Open Targets' tractability assessment is met for any kind of drug.
Gene: Protein-coding gene on chromosome 10 (133,235,769 to 133,241,929, forward strand). Ensembl gene ENSG00000151650.
Subcellular location: Nucleus
Subcellular location (Human Protein Atlas): Nucleoli fibrillar center
Pathways (Reactome):
Cellular responses to stimuli: Senescence-Associated Secretory Phenotype (SASP)
Gene expression (Transcription): Transcriptional Regulation by VENTX
Gene Ontology:
Molecular function: DNA-binding transcription activator activity, RNA polymerase II-specific; protein binding; sequence-specific DNA binding; sequence-specific double-stranded DNA binding; DNA-binding transcription factor activity, RNA polymerase II-specific; RNA polymerase II cis-regulatory region sequence-specific DNA binding; DNA binding
Biological process: positive regulation of transcription by RNA polymerase II; cell differentiation; regulation of transcription by RNA polymerase II; regulation of DNA-templated transcription
Cellular component: chromatin; nucleoplasm; nucleus
Genetic constraint (gnomAD): Loss-of-function variants: 11 observed, 8.09 expected, observed/expected ratio (o/e) 1.36, 90% interval 0.84 to 1.9. That is too few expected variants to judge how well the gene tolerates losing a copy. Missense variants: 329 observed, 278.28 expected, observed/expected ratio (o/e) 1.18, 90% interval 1.08 to 1.29. Synonymous variants: 146 observed, 124.2 expected, observed/expected ratio (o/e) 1.18, 90% interval 1.03 to 1.35.
Homologues: Orthologues: chimpanzee VENTX (97% identical), macaque VENTX (86% identical), dog VENTX (54% identical), zebrafish vent (20% identical), zebrafish bsx (18% identical), Drosophila melanogaster Dll (16% identical), Caenorhabditis elegans ceh-43 (14% identical). Paralogues in human: BSX (18% identical), NANOG (18% identical), NANOGP8 (18% identical), DLX2 (17% identical), DLX5 (16% identical), DLX3 (16% identical), DLX4 (14% identical), DLX1 (13% identical), DLX6 (12% identical).